IL6 (interleukin 6)
Diseases named in the same sentence as IL6 in open-access papers (continued):
Sharing a sentence is not in itself a finding about the gene and the disease.
tumor (continued). "We also found that the IL6-JAK-STAT3 signaling pathway, which drives the proliferation, survival, invasiveness, and metastasis of tumor cells and suppresses the antitumor immune response in the tumor microenvironment, displayed high pathway activity by GSVA analysis in this study." (PMID 32021566, 2020). "Moreover, ELISA assays confirmed that neither MIA PaCa-2 nor AsPC-1 cells alone produced a detectable level of IL6, and SCs alone produced low levels of IL6, while tumor-neuroglia co-cultures showed a four-fold increase of IL6." (PMID 32308766, 2020). "Within the tumor microenvironment, cancer cells and interacting host cells produce a battery of pro-inflammatory cytokines, such as tumor necrosis factor alpha (TNF-α) and Interleukin 6 (IL-6), among many others, that play a central role in the induction and in the course of cancer cachexia." (PMID 32083092, 2020). "Although MUC16-C could promote the secretion of IL6, the effect is not dramatic, and the cells that secrete the most IL6 in the microenvironment are not tumor cells but white blood cells." (PMID 33056994, 2020). "It should be noted, however, that there is also evidence that IL-6 and TNF-a may be antitumorigenic at higher concentrations, suggesting that the local concentration of these cytokines in the tumor microenvironment is a key factor in tumor progression." (PMID 32973746, 2020). "They assessed circulating interleukin-6 (IL-6), VEGF, fasting insulin, and tumor expression of insulin-like growth factor-1 receptor (IGF-1R), insulin receptor (IR), insulin-like growth factor-1 (IGF-1), and RAGE markers before surgery and 6 months after tumor surgery." (PMID 33117687, 2020). "For the non-irradiated tumor in β2-AR KO mice, we noted a significant increase in expression of several genes including Cd28, Il2, and Zap70; genes showing the greatest decrease included genes which can inhibit effector function (including Il6 and Il10)." (PMID 32286326, 2020). "In addition, IL-6 activities in BC were found to be mediated through activation of the bromodomain and extraterminal (BET) protein BRD4 that was required for Notch1-mediated pro-tumor activities." (PMID 32605277, 2020). "In particular, tumor cells release chemokines (such as, SDF-1, MIP-1, MCP-1, MIP-2, etc.)that trigger the activation of SRC kinase in immune cells, which in turn release other cytokines (TNF-α, IL-1β, IL-6, etc.)reciprocally activating SRC in cancer cells through a positive feedback mechanism." (PMID 32545574, 2020). "For example, TGF-β2 can deplete interleukin 6 (IL-6) function and induce apoptosis, TGF-β3 affects the differentiation of mesenchymal stromal cells (MSCs), while TGF-β1 plays an important role in cancer progression and tumour microenvironment (TME) development." (PMID 33114183, 2020). "In contrast, dying tumor cells can stimulate the production of TNF-α, epidermal growth factor (EGF), IL-6, and Wnt ligands, which in turn recruit myeloid cells and fibroblasts to the local TME, serving as anti-cell death signals and decreasing the efficacy of anti-tumor therapies." (PMID 32973519, 2020). "This study also noted that several gp130 cytokines (IL-6, LIF, CT-1, and CNTF) were able to significantly increase the CSC population in HMECs, pointing to their potential role as microenvironmental cytokines capable of promoting tumor progression through STAT3." (PMID 32023849, 2020). "Additionally, studies have also revealed that IL-6 may also support immunosuppression in the TME by repressing the differentiation of IFN-γ-producing helper T cells and promoting subsequent tumor formation." (PMID 33419310, 2020). "Apparently, mGluR1 signaling has a direct effect on tumor cell growth and survival but it also increases inflammation within the tumor microenvironment by upregulating the production of inflammatory chemoattractants such as CXCL1, IL-6, and IL-8 and inducing neutrophil transmigration." (PMID 32973771, 2020).
tumor (continued). "Interestingly, the interaction of MSC with tumor cells modifies their trophic properties through the release of various cytokines such as CXCL1, CXCL2, CXCL12 or IL-6 and metalloproteinases (MMPs) that can degrade the extracellular matrix and promote tumor migration." (PMID 33081024, 2020). "Therefore, all these data suggest that a partial blockade of PDIA3 in T98G cells might attenuate the pro-tumor microglia activation since it tends to reduce the M2 parameters (urea and ARG1) and IL6 release by microglia." (PMID 33153019, 2020). "Moreover, inflammation may be an agent in the process, and various inflammatory cytokines such as IL-6, IL-8, TNF-α, and PGE have impacts on the tumor microenvironment, which could aid tumor progression." (PMID 33003438, 2020). "Nine hallmarks could be related to tumor immunology and collectively showed a decreased expression over time (allograft rejection, complement, IL2-STAT5 signaling, IL-6-JAK-STAT3 signaling, inflammatory response, IFN-α response, IFN-γ response, KRAS signaling up, and TNF-α signaling via NF-κB)." (PMID 31921184, 2019). "In contrast, circulating CD8+ T-cells from peripheral blood of HCC patients present high amounts of pSTAT3 which is correlated with high amount of IL-4, IL-6 and IL-10 and low quantity of IFN-γ which may result in abnormal immune surveillance against tumor cells." (PMID 31480382, 2019). "Moreover, blockade of IL-4 resulted in overexpression of pro-inflammatory cytokines (CXCL10, IL-1β, IL-15, IL-10 and IL-6) and lower expression of immunosuppressive molecules (Foxo3, IDO1 and PD-L1) as compared to cryo-thermal eosinophils + tumour-bearing DCs group." (PMID 31519961, 2019). "However, the authors of these studies did not explore the relationship of IL‐6 levels with tumour cell migration and invasion." (PMID 30582770, 2019). "Therefore, in the tumor inflammatory microenvironment, ionizing radiation effects on NRP1 may regulate IL-17, TNF, IL-6, IL-8 and other inflammatory factors to enhance the radiation resistance of A549 cells." (PMID 31417646, 2019). "In the present study, IL-6 was significantly shown to be modulated by TIMP-1 since genetically silencing TIMP-1 significantly decreased IL-6 mRNA and protein levels under normoxia, as well as hypoxia, the latter being a known critical player in tumor progression." (PMID 31443242, 2019). "IL-6 and IL-11 activate signal transducer and activator of transcription 3 (STAT3), and this canonical pathway may represent a mechanism by which chronic inflammation contributes to tumour initiation and progression." (PMID 31123345, 2019). "It has been reported that fucoidan can be used as an adjuvant by inducing the up-regulation of CD40, CD80 and CD86 expression and production of interleukin-6 (IL-6), IL-12 and tumor necrosis factor-α (TNF-α) in spleen cDCs, which may have an effect on the development of tumor vaccines." (PMID 30897733, 2019). "A majority of PNP cases showed markedly elevated serum IL-6 levels, and recent studies showed that IL-6 is a major driver of disease progression in idiopathic multicentric Castleman disease, which has a substantially higher incidence in PNP than that in other neoplasms." (PMID 31214197, 2019). "Also, IL-6 expression is higher in CC tissue compared to non-tumorigenic adjacent tissue and this overexpression is correlated with tumor size and poor prognosis." (PMID 31396215, 2019). "While tumor burden and treatment were not predictors of survival in the multivariable model, when correcting for BRAF-status and LDH, subjects with high IL-6 and high IL-8 had a 3.1 times increased risk of death (95% CI, 1.4–14.2) compared to subjects with low IL-6 and low IL-8 (p = 0.012)." (PMID 31781510, 2019).
tumor (continued). "Secondly, NLRP12 downregulates hepatocyte-specific expression of cytokines such as IL-6 and TNFα which promote proliferation and tumor growth, and chemokines CXCL1, CXCL2 and CCL2, which enhance inflammatory cell infiltration and thereby augment inflammation in the tumor milieu." (PMID 30990169, 2019). "The assay of the other cytokines, notably IL-6 and IL-8, in the urine of the NMIBC patients could also be important in order to evaluate the immune response presumably involved in the prevention and clearance of the tumor." (PMID 31277459, 2019). "They found higher degree of methylation of MGMT, RARβ, RASSF1A, and CDH13 in tumour specimens and of SOCS-1 in peripheral blood with higher levels of IL-6, while others found less degree of methylation of USP2, TMEM49, SMAD3, DTNB, and IL-6 promoter with higher levels of IL-6." (PMID 31205673, 2019). "Similarly, other proteins released by CAFs, such as IL-6 and TGF-β, could also be targeted in order to improve the anti-tumor immune response." (PMID 31462327, 2019). "These CAFs express interleukin 6 (IL6), C-C motif chemokine 2 (CCL2), and Transforming Growth Factor Beta 3 (TGFB3) that induce the differentiation of peripheral blood mononuclear cell (PBMC) to MDSC, which contributes to T cell depletion in the tumor microenvironment." (PMID 31416205, 2019). "Moreover, the number of IL-6- and IL-8-positive tumour cells positively correlated with TNM stage, and high IL-6 and IL-8 expression was found to indicate poor overall survival of ESCC patients when the medium value of all IL-6 and IL-8 percentages was used as a comparison point." (PMID 31324197, 2019). "As expected, the tumor-bearing DCs co-cultured with cryo-thermal macrophages were highly matured, as demonstrated by the increased percentage of CD11c+CD86+MHC II+ DCs along with the higher relative expression of IL-6, TNF-α, CXCL10, IL-1β, IL-12p40, and IL-15 mRNA." (PMID 30833570, 2019). "Consistent with the DC maturation results, tumour-cell debris after HMME/R837@Lip-augmented SDT could act as an antigen to trigger the highest level of DC-secreted immune cytokines, such as IL-6 and TNF-α, which further demonstrated that the immune adjuvant R837 could enhance the immune response." (PMID 31048681, 2019). "Interestingly, Astragaloside III also strongly elevated the protein levels of IFN-γ, IL-12 but not TNF-a and IL-6 in tumor tissue, indicating the broad immune regulatory activities and restricted over inflammation in tumor." (PMID 31456687, 2019). "The expression of TNF-α, IL-1α, and IL-6 from MDA-MB-231 cells was shown to be inhibited by apigenin, and the inhibition of TNF-α-induced CCL2 release by apigenin was thought to suppress tumor migration and metastasis through the regulation of tumor microenvironment." (PMID 31252615, 2019). "Among this complex network, TAMs are closely related to tumor masses from either circulating monocytes or tissue-resident macrophages, which clearly interact with a wide range of growth factors and cytokines, such as IFN-γ, IL-6, and IL-23, even their function is controversial." (PMID 30483821, 2019). "A murine-transplanted model of the liver tumor showed that HCCs cotransplanted with HSCs could significantly enhance the tumor area and detect more MDSCs compared with HCCs alone or HCCs cotransplanted with HSCs lacking IL-6." (PMID 31614930, 2019). "Our results did not exclude the possibility that MTERFD1 might induce IL-6 and IL-11 production in these tumor stromal cells and infiltrated immune cells to promote CRC development in a paracrine manner; this possibility requires further investigation." (PMID 31754344, 2019). "Interestingly, IL-6 was also the gene which was differentially upregulated in tumor tissue from non-responding patients." (PMID 31730012, 2019).
tumor (continued). "Notably, IL-6-IL-6R interaction not only promotes VEGF-A secretion from classical monocytes but also activates the STAT3 signaling pathway in cancer cells, which enhances tumor cell proliferation in pancreatic ductal adenocarcinoma (PDAC)." (PMID 31474975, 2019). "This liposome could significantly increase the cytokine rations of IL-12/IL-4, IL12/IL-1α, IL-12/IL-1β, IFN-γ/IL-6, IFN-γ/IL-1α, and IFN-γ/IL-1β by 1.18–3.14-fold, (P < 0.05), thus favoring the balance of Th1 and Th2 cells to stimulate antitumor effects in the tumor microenvironment." (PMID 31915707, 2019). "Therefore, the following was determined, first, whether HBD inhibits other related proteins of the IL-6/STA3 signaling pathway, and whether HBD inhibits the expression of genes involved in tumor proliferation." (PMID 30832202, 2019). "In addition, IL-6 correlates with CAF marker ACTA2 and negatively correlates with tumor purity, suggesting that IL-6 is produced primarily by CAFs and not tumor cells." (PMID 30744595, 2019). "Similar to IL-1β, IL-6 is not restricted to the tumor microenvironment." (PMID 31174326, 2019). "Our data showed that nevirapine inhibited distant metastasis of tumor xenografts and phosphorylation of pJAK2 and pSTAT3 proteins in WRO 82‐1 cells, indicating that nevirapine exerts its anticancer effects possibly by inhibiting IL‐6/JAK2/STAT3 signaling pathway." (PMID 31631580, 2019). "NF-kB and STAT3 signaling pathways provoke tumor-stimulating reactions by the production of interleukin-6 (a well-known growth factor for myelomatous plasma cells), prostaglandin E2, matrix metalloproteinases, and RAGE stimulation in the microenvironment of a tumor." (PMID 30836666, 2019). "Several microRNAs were previously found to be released by tumor cells and interact with Toll-like receptors of immune cells, leading to their activation, accompanied by upregulation of NF-κB and secretion of the proinflammatory, prometastatic cytokines TNF-α and IL-6." (PMID 30611259, 2019). "Although IL-6 is not necessary for macrophage recruitment in our model, the upregulation of IL-6 in tumor epithelium may be important for other functions such as tumor initiation, growth, and metastasis." (PMID 30458886, 2018). "The expression of other STAT3-signalling cytokine, such as IL-6, could explain the absence of total tumor regression and the similar cytokine expression and immune infiltration profiles between OSM-KO mice and their WT littermates." (PMID 30559930, 2018). "Moreover, the lack of interleukin-6 in the tumor microenvironment augments type-1 immunity and increases the efficacy of cancer immunotherapy." (PMID 30587227, 2018). "Finally, a multivariate analysis indicated that tumor grade G3 and high IL-6/c-FLIP+PD-L1+CD14+ cells were negative independent prognostic factors for both OS and DFS in this patient’s cohort." (PMID 30518925, 2018). "Similarly, Roccaro and colleagues demonstrated that EVs from bone marrow mesenchymal stem cells transfer several cytokines, such as IL6, CCL2 (also known as MCP1), and junction plakoglobin (also known as γ-catenin), on melanoma cells, promoting tumor growth both on in vitro and in vivo models." (PMID 30532788, 2018). "One explanation for this result is that the level of IL-6 in this tumor might be too low to induce TAM-like cells in HSC-NOG non-Tg mice." (PMID 29456539, 2018). "Differently, in MDA-MB-231 cells the expression of both RANTES and IL-6 cells did not produce a significant increase of the tumor growth in vivo.These results are in agreement with the less pronounced in vitro effects of cytokine overexpression in MDA-MB-231 cells as compared with MCF-7 cells." (PMID 29707128, 2018).
tumor (continued). "Interestingly, icaritin not only inhibited tumor growth but also decreased serum IL-6 and IgE levels, without exhibiting any adverse effects such as body weight loss." (PMID 29899697, 2018). "Additionally, the TG2 gene has regulatory elements that respond to cytokines, including TGF-β, interleukin 6 (IL-6) and tumor necrosis factor alpha (TNF-α), suggesting that the tumor microenvironment may also have a role in increased TG2 expression." (PMID 30200219, 2018). "A very important property of EGFRvIII-expressing tumor cells consists of their capacity to exert paracrine effects on neighbor cells through the release of microvesicles containing the mutant EGFR or mitogenic cytokines, such as interleukin-6 (IL-6) and leukemia inhibitory factor (LIF)." (PMID 30279357, 2018). "Besides the tumor-like behaviors, RA-FLS cells also contribute to pathological destructions through expression of a variety of proinflammatory cytokines or proteinases such as IL-6, interleukin-8 (IL-8), and MMPs." (PMID 29692777, 2018). "Additionally, GCSF, but not IL-6, was upregulated in the BM of tumor-bearing mice relative to controls and in the blood serum of BC patients." (PMID 29593283, 2018). "Conversely, treatment of male LR/Stat3Δ/Δ mice with anti-IL-6 antibody resulted in significantly increased expression levels of immune markers indicative of M1 macrophage polarization, Th1 differentiation and/or cytotoxic (CD8 T/NK cell) anti-tumor response (Ifng, Tbx21, and Gzmb)." (PMID 30389925, 2018). "In 4T1 tumours, the TAMs were the major, but not the only stromal source of IL-6." (PMID 30054470, 2018). "In addition, poly(I:C) induced higher levels of proinflammatory cytokine secretion (IFN-I, IL-6, and CXCL-10), MHC I expression of tumor cells, and monocyte activation in vitro, impairing tumor growth in vitro and in vivo even when TLR signalling was hampered on host cells." (PMID 29854832, 2018). "We have furthermore demonstrated lower expression of TLR4 in HPV+ OPSCC compared to HPV– OPSCC tumor tissue, as well as a lack of IL-6 and IL-8 expression in HPV+ cell lines after stimulation with both LPS and LPS-UP, inferring functional changes in the TLR4 signaling pathway of HPV+ disease." (PMID 29416610, 2018). "Lung tissues with tumor metastasis provided evidence of increased oxidative stress, as assessed by p22phox and SOD mRNA levels and the NRF2 protein level, as well as increased inflammation, as assessed by TNF-α and IL-6 mRNA levels and the NF-κB P65 protein level." (PMID 29433520, 2018). "Furthermore, we show that the cMYC inhibitor JQ1 can reduce BMSC secreted IL-6 in vivo, irrespective of tumor burden." (PMID 29769142, 2018). "As such, its EC-preferential induction in tumor microenvironment, but dispensability in development, suggests that IL-6 may present a highly selective and non-noxious therapeutic target for cancer treatment." (PMID 29422647, 2018). "Both expression and nuclear translocation of EGR1 were reduced in F4/80+ TAMs in Il6−/− tumours, suggesting that loss of nuclear EGR1 expression might be responsible for the reduction of FAP expression by TAMs in the absence of IL-6." (PMID 30054470, 2018). "IL-6-mediated inflammation may be more prevalent in irEC than in the responding tumors; targeting IL-6 may ameliorate irEC without hindering anti-tumor immunity." (PMID 30400822, 2018). "Moreover, many therapies targeting tumor cells already decrease IL-6 or pathways downstream of IL-6, so that no additive or synergistic effect is derived from the anti-IL-6 therapy." (PMID 30671025, 2018). "The TME not only plays a supporting role for various cells, including tumor cells, immune cells, vascular endothelial cells, and fibroblasts but also forms the ECM (including collagen, laminin, and proteoglycan complexes) and secretes multiple cytokines, such as SDF-1, IL-6, bFGF, and EGF." (PMID 30355650, 2018).